JAK2 (Janus kinase 2)
Diseases named in the same sentence as JAK2 in open-access papers (continued):
Sharing a sentence is not in itself a finding about the gene and the disease.
melanoma (continued). "The Janus kinase-2 (Jak2)-signal transducer and activator of transcription-3 (STAT3) pathway is critical for promoting an oncogenic and metastatic phenotype in several types of cancer including renal cell carcinoma (RCC) and melanoma." (PMID 22899991, 2012). "Together, these findings not only demonstrate that SOID-8 blocks the JAK2/STAT3 signaling in vitro and in vivo, but also provide a potential novel lead compound for further development of new preventive and therapeutic agents for melanoma." (PMID 23166634, 2012). "Melanoma tumors from non-responders to ipilimumab have displayed a higher frequency of mutations such as copy-number alterations in IFN-γ pathway genes, including IFNGR1, IRF1, and JAK2, than that from the responders." (PMID 37614504, 2023). "Hence, combining with the results of survival and Cox regression analyses, it implied that the high expressions of IRF1, JAK2, CD8A, and SELL may predict a positive response to anti-PD-1 immunotherapy for melanoma patients." (PMID 32316408, 2020). "Thus, our results indicating significant basal activation of JAK2, SRC, STATs 1, 3, and 5, in melanoma aids in resolving finer aspects of STAT1 vs. STAT3 as well as acts as a springboard for dissecting studies on cytokine-induced STAT mediated cross-talks between JAK and SRC pathways." (PMID 28223541, 2017). "However, whether the JAK2/STAT3 signaling pathway participates in the proangiogenic switch of CAFs in melanoma microenvironment has not been reported." (PMID 30285793, 2018). "Our findings demonstrate that the amentoflavone analogue compound 1 is a potent inhibitor of the JAK2/STAT3 signaling pathway against melanoma cells, suggesting that this natural product scaffold could deserve further attention for the development of anti-melanoma therapeutics." (PMID 28570563, 2017). "The most potent analogue, compound 1, inhibited the phosphorylation of JAK2 and STAT3 in human melanoma cells, but had no discernible effect on total JAK2 and STAT3 levels." (PMID 28570563, 2017). "Compound 1 reduced the phosphorylation of JAK2 and STAT3 in A375 melanoma cells, but had no discernible effect on total JAK2 and STAT3 levels." (PMID 28570563, 2017). "RGP, VGP and MET cell lines all express both JAK1 and JAK2, further indicating that the major components of the MHC II signaling pathway are intact, regardless of the stage of melanoma progression." (PMID 25690042, 2015). "Finally, the results suggested that the expression of six genes including IRF1, JAK2, CD8A, IRF8, STAT5B, and SELL had a significant ability to distinguish the responders from non-responders to anti-PD-1 therapy in melanoma with AUC > 0.6 and pAUC > 0.7." (PMID 32316408, 2020). "Basal level phosphorylation of GH-regulated intracellular signaling networks like JAK2, STATs 1, 3, 5, ERK1/2, SRC, AKT and mTOR in absence of externally added GH suggested the presence of an autocrine ligand-receptor loop existent and critical in these four melanoma cell lines." (PMID 28223541, 2017).
colorectal cancer (117 papers, 2010 to 2025). A primary or metastatic malignant neoplasm that affects the colon or rectum. "Reduced GNAI1 expression has been reported in hepatocellular carcinoma, where it is associated with increased tumor cell migration and invasion, as well as in colorectal cancer metastasis, where its loss enhances angiogenesis through activation of JAK2/STAT3 signaling and upregulation of VEGFA." (PMID 41550951, 2025). "The findings of this study demonstrate that STA exerts an inhibitory effect on colorectal cancer liver metastasis by targeting macrophages and impeding their M2 polarization via the JAK2/STAT3 pathway." (PMID 39974738, 2025). "Oridonin inhibits Wnt/ β- Chain protein signaling pathway, TGF- β The 1/Smads PAI-1 signaling pathway, colon cancer cell metastasis and JAK2/STAT3 signaling pathway to resist colorectal cancer." (PMID 40324265, 2025). "Baicalein induces ferroptosis in colorectal cancer cells by the janus kinase 2 (JAK2)/ signal transducer and activator of transcription 3 (STAT3)/ glutathione peroxidase 4 (GPX4) pathway." (PMID 41460836, 2025). "PRRX1 upregulation promotes proliferation, stemness, and chemoresistance in colorectal cancer cells by activating the interleukin-6 (IL-6)/JAK2/STAT3 axis, with IL-6 inhibition reversing its effects on stemness and chemoresistance." (PMID 40860778, 2025). "Previous studies have shown that TRIM family proteins regulate colorectal cancer cell proliferation, migration, and invasion through the JAK2/STAT3 pathway." (PMID 40075566, 2025). "Human colorectal cancer-derived MSCs enhanced the growth and metastasis of colorectal cancer cells in vitro and in vivo via the IL-6/JAK2/STAT3 signaling pathway." (PMID 38951845, 2024). "Interleukin-6 a pleiotropic cytokine involved in immune regulation and activation of JAK2/STAT3 pathway in colorectal cancer." (PMID 38869738, 2024). "Reportedly, FGFR2 contributes to activating the JAK2/STAT3 pathway in colorectal cancer, resulting in the promotion of PD-L1 expression." (PMID 38326861, 2024). "Previously, our laboratory has demonstrated that anlotinib combined with DDP significantly inhibited the proliferation of colorectal cancer (CRC) cells by antagonizing the VEGFR/Janus kinase 2 (JAK2)/signal transducer and activating transcription-3 (STAT3)." (PMID 39508048, 2024). "Specifically, FGFR2 has been identified as a driver of M2 macrophage polarization in colorectal cancer by increasing PAI-1 expression via the JAK2/STAT3 pathway." (PMID 39436561, 2024). "It has further been shown that CD276 (B7-H3) increases the ability of colorectal cancer cell lines to resist apoptosis by activating the Janus kinase 2-signal transducer and activator of transcription 3 (JAK2-STAT3) pathway." (PMID 39911580, 2024). "Mesenchymal stem cells derived from human CRCs facilitate colorectal cancer progression via the IL-6/JAK2/STAT3 signaling pathway." (PMID 38673975, 2024). "IL-6 activates autophagy through the upregulating JAK2 pathway and promotes chemotherapy resistance in colorectal cancer." (PMID 36751636, 2023). "ZNF460 (zinc finger protein 460) is involved in the regulation of multiple cancer processes by JAK2/STAT3 pathway, and its high expression is associated with the proliferation, invasion, and metastasis of colorectal cancer and oral cancer." (PMID 36639776, 2023). "Human mesenchymal stem cells derived from colorectal cancer have been shown to promote the progression of colorectal cancer through the IL-6/JAK2/STAT3 signaling pathway." (PMID 37958803, 2023). "miR-181 family is reported to be susceptible to SNHG6, and as a result, upregulation of JAK2 by SNHG6 overexpression has been reported to suppress apoptosis in Colorectal Cancer, where JAK2 is a known inhibitor of apoptosis and promoter of cancer growth." (PMID 37735423, 2023). "In another study, berberine was reported to hinder the COX-2/PGE2-mediated JAK2/STAT3 signaling pathway in colorectal cancer cell invasion and metastasis." (PMID 36144625, 2022).
colorectal cancer (continued). "In colorectal cancer, IL-6 activates autophagy by the interaction of JAK2 and Becn1 because JAK2 acts as a protein kinase that phosphorylates Becn1 at Y333 to promote autophagy initiation." (PMID 36311768, 2022). "The activated JAK2/STAT3 pathway transcriptionally inhibited the tumor suppressor miR-506-3p in colorectal cancer (CRC) cells, which in turn led to pulmonary metastases." (PMID 35356244, 2022). "This study elucidated that the efficacy of anti-cancer reagent was mediated by JAK2/STAT3 signaling pathway in colorectal cancer HCT116 and SW480 cells." (PMID 35207737, 2022). "Here the authors show that IL-6 activates autophagy in colorectal cancer through the interaction between JAK2 and autophagy regulator, BECN1, which leads to chemotherapeutic resistance." (PMID 34131122, 2021). "Another investigation has proved the crosstalk between JAK2 and mTOR in the regulation of colorectal cancer." (PMID 34316408, 2021). "In advanced colorectal cancer, the JAK2/STAT3 signaling pathway can regulate the growth of cancer stem cells and even reverse the effects of radiotherapy, contributing to resistance to radiotherapy." (PMID 33788424, 2021). "Previous studies have indicated that hispidulin inhibits the Janus kinase 2 (JAK2)/STAT3 pathway by generating ROS in colorectal cancer cells, and downregulates the expression of the oncogene PIM1." (PMID 34356663, 2021). "In radiotherapy‐resistant advanced colorectal cancer tissues, the JAK2/STAT3 signaling pathway plays a role in promoting tumorigenesis and drug resistance by inhibiting cell apoptosis and enhancing cell cloning potential." (PMID 33788424, 2021). "Mechanistically, IL-6/JAK2 signaling-mediated phosphorylation of BECN1 at Y333 by contributes to chemotherapy resistance in colorectal cancer, and the pharmacological inhibition of autophagy leads to reestablishment of chemotherapy sensitivity." (PMID 34131122, 2021). "We further show that the level of BECN1 Y333 phosphorylation is a predictor of colorectal cancer patient outcome and that JAK2 inhibitor treatment combined with chemotherapy is more effective in inhibiting cancer cell growth." (PMID 34131122, 2021). "The initiation of autophagy induced by the IL-6/JAK2/BECN1 signaling pathway appears to be a regulatory mechanism for chemotherapy resistance in colorectal cancer." (PMID 34131122, 2021). "In the present study, we demonstrated that IL-6 activates autophagy in colorectal cancer, leading to the interaction between JAK2 and BECN1." (PMID 34131122, 2021). "MiR-4449 promoted cell proliferation and JAK2/STAT3 signaling activity by inhibiting SOCS3 in colorectal cancer." (PMID 34691358, 2021). "The result is consistent with promotion of cell migration and invasion MMP-9 through the Jak2/Stat3/MMP9 signaling pathway in B7‐H3 stimulation in colorectal cancer." (PMID 33228717, 2020). "In colorectal cancer, through the Janus kinase (JAK2)/signal transducer and activator of transcription (STAT3) signaling pathway, activation of α7-nAChR in tumor macrophages inhibits colorectal cancer metastasis." (PMID 33299855, 2020). "In colorectal cancer, the activation of α7nAChR in tumor macrophages inhibits colorectal cancer metastasis through the JAK2/STAT3 signaling pathway." (PMID 31068932, 2019). "IL-6 was the most highly expressed cytokine in the human colorectal cancer-derived mesenchymal stem cells conditioned medium, and promoted the progression of colorectal cancer cells through IL-6/JAK2/STAT3 signaling, which activated PI3K/AKT signaling." (PMID 30175384, 2018). "In brief, our results indicate that CC-MSCs enhance colorectal cancer progression through the activation of IL-6/JAK2/STAT3 signaling." (PMID 29348540, 2018). "Mechanistically, we determined that interleukin-6 (IL-6) was the most highly expressed cytokine in the CC-MSC conditioned medium, and promoted the progression of colorectal cancer cells through IL-6/JAK2/STAT3 signaling, which activated PI3K/AKT signaling." (PMID 29348540, 2018).
colorectal cancer (continued). "STAT3 protein (downstream of JAK2) was found to be over-expressed and persistently activated in alimentary canal cancers, such as esophageal, stomach and colorectal cancers." (PMID 28186962, 2017). "In summary, our study observed that miR-375 suppressed the cell proliferation and tumor formation in colorectal cancer by mainly targeting both JAK2/STAT3 and MAPK/ERK signaling pathways." (PMID 28186962, 2017). "illustrated the biological significance of JAK2/STAT3 signaling for colorectal cancer apoptosis and provided novel evidence that the inhibition of JAK2/STAT3 induced apoptosis via the mitochondrial apoptotic pathway." (PMID 23483946, 2013). "IC50 values (μM) of FLLL32, curcumin, and other JAK2/STAT3 or STAT3 SH2 inhibitors in human colorectal cancer cells (C), glioblastoma cells (G), multiple myeloma (MM) and liver (L) cancer cells." (PMID 20712901, 2010). "Furthermore, miR-155 derived from colorectal cancer Exo stimulates the activation of fibroblasts through the SOCS1/JAK2/STAT3 signaling pathway." (PMID 40486266, 2025). "Furthermore, the observed sex-specific differences, with enhanced activation of the JAK2/STAT3 axis in male UC patients, shed light on their elevated risk for colorectal cancer development." (PMID 40761789, 2025). "IL-6 has been implicated as mediator of tumor progression and chemoresistance in multiple cancers such as NSCLC and colorectal cancer wherein IL-6 has been observed to modulate autophagy by inducing phosphorylation of BECN1 via the IL-6/JAK2/BECN1 signaling pathway." (PMID 40176914, 2025). "Similarly, ZNF667-AS1 suppressed the progression of colorectal cancer through affecting ANK2/JAK2 axis." (PMID 39425009, 2024). "For example, Beclin1/autophagy signaling mediates Sox2-promoted chemoresistance, proliferation, stemness, migration, and invasion in colorectal cancer cells, and IL-6 activates autophagy via the IL-6/JAK2/BECN1 pathway, promoting chemotherapy resistance in colorectal cancer." (PMID 37303041, 2023). "Moreover, trichostatin A (TSA) leads to the hyperacetylation of histones associated with SOCS1 and SOCS3 promoters, which significantly downregulates JAK2/STAT3 signaling in colorectal cancer cells." (PMID 35611249, 2022). "Moreover, previous studies have shown that ENC1 promotes the progression of colorectal cancer through JAK2/STAT5/AKT axis-mediated epithelial-mesenchymal transition and stemness." (PMID 35992347, 2022). "CD276 impacts colorectal cancer cell migration through the Jak2/Stat3/MMP-9 signaling pathway." (PMID 35296518, 2022). "NOVA1 enhanced IL-6/JAK2/STAT3 signaling in turn to up-regulate MMPs in colorectal cancer." (PMID 36284263, 2022). "Furthermore, it was recently reported that inhibition of JAK2 signaling pathway induced apoptosis in colorectal cancer cells." (PMID 35207737, 2022). "The Janus kinase (JAK) inhibitors could inhibit tumor growth in gastric and colorectal cancer via suppressing the IL-6/JAK2/signal transducer and activator of transcription 3 (STAT3) pathway and enhancing the secretion of anti-tumor cytokines." (PMID 30658426, 2019). "Collectively, these results reveal that the IL-6 secreted by CC-MSCs enhances the progression of colorectal cancer cells through IL-6/JAK2/STAT3 signaling, and could provide a novel therapeutic or preventive target." (PMID 29348540, 2018). "In conclusion, siRNA targeting of B7-H4 effectively suppressed the proliferation, invasion, and migration of LOVO cells by inhibiting the effect of CXCL12/CXCR4 and the phosphorylation of JAK2/STAT3 on increasing the metastatic potential of colorectal carcinoma." (PMID 26078947, 2015).
colorectal cancer (continued). "By blocking the JAK2/STAT3 signaling pathway, ATL I also decreases the proliferation and causes apoptosis of human colorectal cancer cells HCT116 and SW480, slows glycolysis in CRC cells by reducing HK2 expression, and inhibits tumor growth in xenograft colorectal cancer mice." (PMID 37241729, 2023). "Moreover, previous studies revealed that the inhibition of PCSK9 might have an oncogenic role in the development and progression of colorectal cancer by inhibiting JAK2/STAT3 signaling." (PMID 37896137, 2023). "In addition, circSPARC may upregulate the expression of janus kinase 2 (JAK2) by competitively binding to miR-485-3p, and might augment the migration and/or invasion of colorectal cancer." (PMID 37104005, 2023). "It has been reported that cnLOH is associated with JAK2 or FLT3 internal tandem duplication with oncogenic mutations in acute myeloid leukemias and may also contribute to inactivating tumor suppressor genes in colorectal cancer, for example hMLH1." (PMID 25373456, 2014). "Meanwhile, IL-6 induced chemotherapeutic resistance by activating autophagy via IL-6/JAK2/BECN1 signaling pathway, as seen in colorectal cancer." (PMID 40160826, 2025). "In colorectal cancer, NR1H4 activation suppresses the JAK2/STAT3 signaling pathway via trans-activation of the suppressor of cytokine signaling 3 (SOCS3) gene and antagonizes Wnt/β-Catenin signaling, acting as a tumor suppressor." (PMID 40656893, 2025). "For example, TAMs have been shown to regulate the IL-6/JAK2/STAT3/miR-506-3p/FoxQ1 axis, which enhances colorectal cancer (CRC) motility and invasion through the induction of EMT and upregulation of CCL2, promoting macrophage recruitment." (PMID 40083697, 2025). "In colorectal cancer (CRC) cell lines, B7-H3 has been shown to enhance resistance to apoptosis through the upregulation of the JAK2/STAT3 signaling pathway, resulting in an increased expression of anti-apoptotic proteins such as Bcl-2 and Bcl-xL." (PMID 40214484, 2025). "In colorectal cancer, convallatoxin suppresses proliferation and angiogenesis via cooperation between the mTOR/STAT3 and JAK2/STAT3 pathways." (PMID 40321161, 2025). "SOX13 is induced by hepatocyte growth factor through the JAK2/STAT3 signaling pathway, promoting metastasis in colorectal cancer by upregulating SNAI2 and c-MET expression." (PMID 39726600, 2024). "For example, colorectal cancer-derived mesenchymal stem cells promoted EMT and increased the migration and invasion of colorectal cancer by activating IL-6/JAK2/STAT3 signaling." (PMID 38182570, 2024). "Additional studies have observed that curcumin inhibits IL-6/JAK/STAT3 signaling by significantly reducing the phosphorylation of JAK2 and STAT3 levels in colorectal cancer (CRC) cells." (PMID 38673967, 2024). "In colorectal cancer (CRC), TAMs induce EMT program to enhance CRC migration, invasion, and CTC-mediated metastasis by regulating the JAK2/STAT3/miR-506-3p/FoxQ1 axis, which in turn leads to the production of CCL2 that promote macrophage recruitment." (PMID 36817086, 2023). "Overexpression of lncRNA ZNF667-AS1 in colorectal cancer inhibited cell propagation, migration, and metastasis by controlling the ANK2/JAK2 signaling pathway." (PMID 35813862, 2022). "Similar to our result, other researchers have indicated that histone deacetylase inhibitor TSA suppresses the growth of colorectal cancer cells, and induces apoptosis through SOCS1 and SOCS3 upregulation and JAK2/STAT3 signaling inhibition." (PMID 34319031, 2021). "In the present study, we demonstrate that IL-6 activates autophagy through the IL-6/JAK2/BECN1 pathway and promotes chemotherapy resistance in colorectal cancer (CRC)." (PMID 34131122, 2021). "The JAK2/STAT3 signaling pathway mediates the function of solute carrier family 6 member 14 (SLC6A14) to promote the proliferation and metastasis of colorectal cancer cells." (PMID 34895038, 2021).